IQGAP2 (IQ motif containing GTPase activating protein 2)
Diseases named in the same sentence as IQGAP2 in open-access papers (continued):
Sharing a sentence is not in itself a finding about the gene and the disease.
tumor (continued). "Decreased IQGAP2 expression is observed in most patients with HCC and is associated with larger tumor size, advanced tumor stage, and poorer tumor differentiation, as well as shorter postoperative tumor-free survival and overall survival after hepatectomy." (PMID 35785216, 2022). "IQGAP1 and 3 are upregulated and are considered oncogenes in HCC, while IQGAP2 is downregulated and functions as a tumor suppressor." (PMID 35785216, 2022). "Indications from other tumor entities have proved that wnt signaling is also an important pathway involved in IQGAP2′s functional role." (PMID 36362301, 2022). "Consistent with the predominant expression of IQGAP2 in the liver, convincing evidence supports a tumor suppressor role for IQGAP2 in HCC." (PMID 35785216, 2022). "The IQGAP family has two other proteins (namely, IQGAP2 and IQGAP3); of these, IQGAP2 appears to possess tumor-suppressive properties." (PMID 36276098, 2022). "In contrast to isoform 1 and 3 of IQGAP, IQGAP2 is considered a tumor suppressor in HCC since its expression coincides with patient prognosis and is decreased in HCC tissues." (PMID 35785216, 2022). "We also analyzed the protein expressions of IQGAP2 in the FFPE tumor tissue samples of 11 MIBC cases and 7 matched NMIBC cases through immunohistochemistry." (PMID 36362301, 2022). "IQGAP2 was first classified as a tumor suppressor expressed in the liver and was reported to regulate the PI3K/Akt and Wnt/β-catenin signaling pathways." (PMID 33613306, 2021). "While IQGAP2 shares an overall 62% homology with IQGAP1 with even higher levels of homology between their respective structural motifs except the WW domain, IQGAP2 surprisingly possesses tumor suppressive activities." (PMID 33498739, 2021). "IQGAP2 depletion, in a tumor xenograft model, increased tumor volume, tumor weight, and phospho-ERK expression." (PMID 33846302, 2021). "Despite their 62% sequence identity, IQGAP1 is an oncogene, while IQGAP2 has been reported as a tumour suppressor in hepatocellular, prostate, and gastric carcinomas." (PMID 34034707, 2021). "IQGAP2 has been proposed to be a tumour suppressor and its expression is downregulated when IQGAP1 is overexpressed in hepatocellular carcinoma, while IQGAP3 shows oncogenic properties." (PMID 33672268, 2021). "We have previously demonstrated IQGAP2 as a potential tumor-suppressor and noticed a high level of conservation between IQGAP1 and IQGAP2." (PMID 33266355, 2020). "IQGAP2 expression is mainly restricted to the liver, where it appears to have tumor suppressor functions." (PMID 31363101, 2019). "This expression pattern of these two IQGAP isoforms across different cancer types supports the notion that IQGAP2 possibly plays the role of a tumor suppressor gene whereas IQGAP3 is more likely to be an oncogene." (PMID 29073199, 2017). "In contrast, IQGAP2 acts as a tumor suppressor in the liver by regulating Wnt/β-catenin and PI3K/Akt signaling." (PMID 26047140, 2015). "The tumor suppressing repertoire of IQGAP2 has been recently expanded to two additional cancer types: gastric and prostate." (PMID 26047140, 2015). "It was discovered that 86% of Iqgap2−/− mice developed liver tumors at between 18 and 24 months of age, whereas wild-type littermates were completely tumor-free at any age." (PMID 23951254, 2013). "Our previous work identified IQ-motif containing GTPase-activating protein 2 (IQGAP2) as a novel putative tumor suppressor in HCC." (PMID 23951254, 2013). "Compelling recent data have introduced IQGAP2 as the newest addition to the long list of HCC-related tumor suppressors and potential molecular targets for much needed curative therapy." (PMID 22973521, 2012). "IQGAP2 was shown to be expressed at significantly reduced levels in tumor specimens from patients with both advanced and androgen-independent prostate cancers." (PMID 22973521, 2012).
tumor (continued). "Mounting compelling evidence in support of IQGAP2 acting as a tumor suppressor in HCC and other cancers calls for further thorough studies of this intriguing protein." (PMID 22973521, 2012). "In contrast, IQGAP2, which is downregulated in BCa, may function to inhibit tumor proliferation, migration, and invasion by regulating the MAPK/ERK signaling pathway and cytokines." (PMID 40361412, 2025). "These experiments validated the tumor suppressor role of IQGAP2 in ccRCC." (PMID 39039052, 2024). "Evidence has reported that IQGAP2 functioned as a tumor suppressor in malignancies." (PMID 39039052, 2024). "Interestingly, accumulating evidence has demonstrated that IQGAP2 inactivates the canonical AKT signaling pathway to exert the tumor suppressor roles." (PMID 39039052, 2024). "To further elucidate the functional significance of IQGAP2 in the tumor suppressor role of ALDH9A1 in ccRCC, we introduced shRNA to achieve stable silencing of IQGAP2 in A498 and CAKI-1 cell lines, accompanied by transfection with ALDH9A1 overexpression lentivirus or control." (PMID 39039052, 2024). "Our subcutaneous tumor xenografts studies revealed that the enforced expression of ALDH9A1 remarkably restrained the tumor growth in comparisons with the vector group, whereas the knockdown of IQGAP2 reversed the impact of ALDH9A1 overexpression on the tumor growth." (PMID 39039052, 2024). "On the other hand, in terms of its role in cancer, several studies have suggested that IQGAP2 may act as a tumor-suppressor gene." (PMID 38138996, 2023). "There is substantial evidence that IQGAP2 plays a tumor suppressor role in HCC." (PMID 36831467, 2023). "However, IQGAP2 was generally low-expressed in tumor samples, which is expected of a tumor-suppressing entity." (PMID 36362301, 2022). "Immunohistochemistry staining showed that IQGAP2 was strongly expressed in normal tissues in the cytoplasm and cell membrane, especially in the cell-cell junctions, while it was significantly decreased in tumor tissues." (PMID 36320006, 2022). "Both IQGAP1 and IQGAP3 are considered oncogenes in HCC and, thus, can serve as highly sensitive and specific biomarkers for this type of tumor, while IQGAP2 may act as a tumor suppressor." (PMID 36559011, 2022). "Further, we tested the effect of IQGAP2 on tumor growth in vivo, using a tumor xenograft model." (PMID 33846302, 2021). "IQGAP2 knockdown significantly increased both tumor volume and weight." (PMID 33846302, 2021). "We found reduced expression of IQGAP2 in tumor tissue compared to normal tissue." (PMID 33846302, 2021). "Moreover, cumulative evidence from clinical specimens supports that IQGAP2 functions as a potential tumor suppressor." (PMID 32183047, 2020). "Collectively, a careful summarisation of previously reported data and key indications for our in-silico investigation suggest that IQGAP2 might play a role as a tumor suppressor other cancer types as well." (PMID 29073199, 2017). "IQGAP2 displays anti-tumor activity, despite its structural similarity to IQGAP1." (PMID 24849319, 2014). "IQGAP1 has well documented oncogenic potential and IQGAP2 has putative tumor-suppressive function." (PMID 24849319, 2014). "ANKRD40, HNRNPF, IQGAP2, OTUD7B, and THAP5 mutations were detected in 1 tumor, each." (PMID 24223926, 2013). "This suggests that IQGAP2, being a scaffolding protein, may realize its tumor suppressing function through cross-linking several signaling pathways in liver, and that the Wnt/β-catenin pathway is one of them." (PMID 23951254, 2013). "Several studies have already suggested the tumor suppressing activity of IQGAP2." (PMID 22539939, 2012). "According to a proposed model, IQGAP2 plays the role of a tumor suppressor by being a part of the APC/AXIN/GSK3β complex, binding cytoplasmic β-catenin and preventing it from dephosphorylation and, subsequently, from activating β-catenin's nuclear target genes." (PMID 22973521, 2012).
tumor (continued). "In addition to the role as a tumor suppressor, IQGAP2 is also found to be a novel interferon-alpha (IFN-α) antiviral effector gene and may play a role in regulating interferon stimulated genes (ISG) through the NF-κB pathway unconventionally." (PMID 34276655, 2021). "Previous research has indicated the tumor-suppressing role of IQGAP2 in cancers, so we selected T24 and TCCSUP cells with high IQGAP2 expression for siRNA transfection to construct knockdown cell models." (PMID 36362301, 2022). "In addition, when analyzing the mRNA expression of IQGAP2 with Timer using the TCGA dataset, the outcome showed a significantly reduced expression of IQGAP2 in tumors (n = 408) compared to normal bladder tissue (n = 19), as well as reduced expression compared to most other tumor entities." (PMID 36362301, 2022). "In contrast, IQGAP2 is thought to play the opposite role of IQGAP1 in HCC, displaying functions resembling a tumor suppressor." (PMID 36320006, 2022). "The results showed that the patients in tumor tissues with high IQGAP1 expression, low IQGAP2 expression, and high IQGAP3 expression had the shortest survival time, which is consistent with our findings." (PMID 36320006, 2022). "We also demonstrate that IQGAP2 is an inversely survival-related marker in DLBCL, which differs from its role in other tumours." (PMID 34034707, 2021). "In the present study, we have checked differences in mRNA levels of IQGAP2 and IQGAP3 between tumor and normal tissues in the most commonly occurring human cancers viz." (PMID 29073199, 2017). "Oncomine was used to find out differences in mRNA expression of IQGAP2 and IQGAP3, between tumor and normal tissue, in multiple cancers." (PMID 29073199, 2017). "Spontaneous development of HCC in the majority of Iqgap2−/− mice suggests a protective role of IQGAP2 protein in liver, identifying it as a novel tumor suppressor." (PMID 23951254, 2013). "In the present study, our aim was to examine IQGAP1 and IQGAP2 expression in human HCC, their sensitivity and specificity as biomarkers of this type of tumor, and the methylation profile of the Iqgap2 promoter." (PMID 20977743, 2010). "Viewed collectively, these data strongly suggest that IQGAP1 and IQGAP2 contribute to the pathogenesis of HCC, and that these proteins are highly sensitive and specific biomarkers of this type of tumor." (PMID 20977743, 2010). "IQGAP2 and IQGAP3 are both correlated with the MAPK/ERK pathway, which is one of the most crucial signaling pathways in the progression of cancer, promoting tumor growth and metastasis." (PMID 36831467, 2023). "Unlike the oncogene IQGAP1, IQGAP2 is considered to be a tumor suppressor (Smith, Hedman & Sacks, 2015)." (PMID 36275458, 2022). "IQGAP2, a member of the IQGAP family, functions as a tumor suppressor in most of the cancers." (PMID 33846302, 2021). "The overall survival of patients with increased IQGAP2 mRNA levels was reduced even after aggressive treatment independent of age, tumour stage, serum LDH concentration, performance status, and the number of extra nodal disease sites." (PMID 34034707, 2021). "Our conventional knockout Iqgap2−/− mice represent a new HCC model involving a tumor suppressor not studied before." (PMID 23951254, 2013). "Indeed, recent research indicate also that IQGAP1 and IQGAP2 fulfill distinct functions in tumorigenesis, whereas IQGAP1 acts as an oncogene IQGAP2 seems to act as a tumor suppressor." (PMID 24281338, 2012). "Notably, the overexpression and methylation patterns of APMAP, IQGAP2, and FASN in LAR cell lines support a hypothesis of epigenetically regulated tumor cell expression that is retained despite in vitro culturing." (PMID 40155623, 2025).
tumor (continued). "Notably, the triglyceride concentration detection and oil red staining assays revealed a significant reduction in lipid accumulation in the tumor xenografts from ALDH9A1-overexpressing groups, thereby counteracting the observed upregulation of lipid accumulation in the IQGAP2-knockdown group." (PMID 39039052, 2024). "Thus, here we supposed that in ccRCC, the attenuation of ALDH9A1 fails to retain NPM1 in the cytoplasm and promote its accumulation in the nuclear, leading to inhibition of IQGAP2 and subsequent activation of AKT-mTOR signaling to support tumor progression and lipid accumulation." (PMID 39039052, 2024). "Univariate analysis showed that larger tumor size, multiple tumor numbers, microvascular invasion, poor tumor differentiation, advanced TNM stage, positive IQGAP1, negative IQGAP2, and positive IQGAP3 expressions were prognostic factors for RFS." (PMID 36320006, 2022). "Multivariate analysis indicated that multiple tumor numbers, positive IQGAP1, negative IQGAP2, and positive IQGAP3 expressions were independent prognostic factors for RFS." (PMID 36320006, 2022). "Multivariate analysis indicated that multiple tumor numbers, advanced TNM stage, positive IQGAP1, negative IQGAP2, and positive IQGAP3 expressions were independent prognostic factors for OS." (PMID 36320006, 2022). "Besides, univariate analysis showed that multiple tumor numbers, microvascular invasion, poor tumor differentiation, advanced TNM stage, positive IQGAP1, negative IQGAP2, and positive IQGAP3 expressions were prognostic factors for OS." (PMID 36320006, 2022).
cancer (25 papers, 2010 to 2024). A tumor composed of atypical neoplastic, often pleomorphic cells that invade other tissues. "We selected TCGA datasets of all eight cancers to study mutation and copy number change in IQGAP2 and IQGAP3." (PMID 29073199, 2017). "Selective downregulation of IQGAP2 in cancers might be related to somatic mutations, role of methylation remains to be ascertained." (PMID 29073199, 2017). "In this review, we comprehensively reviewed the significant roles of IQGAP2 and IQGAP3 in cancer-associated pathways as well as the role in carcinogenesis and progression of different cancer entities." (PMID 36831467, 2023). "IQGAP1 and IQGAP3 were significantly elevated in cancer tissues and considered oncogenic factors; whereas, IQGAP2 was significantly decreased in cancer tissues and was considered a cancer suppressor." (PMID 36320006, 2022). "As previously demonstrated in numerous studies, IQGAP2 can suppress the metastasis of several types of cancer." (PMID 36362301, 2022). "The reduced expression of IQGAP2 in cancer cells is correlated with cell proliferation, migration, invasion, apoptosis, angiogenesis, and clinical characteristics." (PMID 36362301, 2022). "Then, we checked the IQGAP2 mRNA expression in urinary tract cancer cell lines using the Cancer Cell Line Encyclopedia (CCLE)." (PMID 36362301, 2022). "Currently, many studies have been conducted to evaluate the relationship between IQGAP2 and cancers." (PMID 34276655, 2021). "The authors demonstrated that IQGAP2 can suppress the transcriptional activity of β-catenin, a downstream protein in Wnt signaling, which leads to an inhibition of cancer cell epithelial-mesenchymal transition, migration, and invasion." (PMID 34943212, 2021). "In conclusion, our data show that IQGAP2 mRNA is more highly expressed in several cell lines derived from haematologic malignancies compared to most other cancer cell lines." (PMID 34034707, 2021). "On the other hand, SOCS2 and IQGAP2 relay interactions with factors that are released by immune cells, including various types of cytokines, potentially allowing for cancer cells to be aware of the immune environment." (PMID 31480259, 2019). "Overall, we observed that while IQGAP3 was elevated in most cancer types at both mRNA and protein level, IQGAP2 was reduced in expression." (PMID 29073199, 2017). "Among the different cancer types and their respective sub-types, we mostly found reduced and elevated mRNA levels of IQGAP2 and IQGAP3, respectively, which coincided with poor survival rates of patients." (PMID 29073199, 2017). "Reduced expression of IQGAP2 has been found in cancers of gastric, liver, prostate and ovarian origin." (PMID 29073199, 2017). "The expression pattern and role of IQGAP1 has been well established in many cancers, whereas those of IQGAP2 and IQGAP3, have mostly remained unexplored." (PMID 29073199, 2017). "This is of particular relevance to HCC, because targeted ablation of cdc42 in mouse hepatocytes and bile ducts resulted in the development of HCC, closely resembling the cancer in Iqgap2 −/− mice in terms of late onset and molecular signature of the tumors." (PMID 22973521, 2012). "Interestingly, some studies highlighted the reciprocal expression pattern of IQGAP1/IQGAP2 in cancers, hinting at tight regulation of one isoform over another." (PMID 33846302, 2021). "IQGAP2 is decreased in several cancers, including hepatocellular, prostate, and gastric carcinomas." (PMID 34034707, 2021). "As reduced IQGAP2 expression was frequently observed in several cancers which correlated with poor survival, we examined the expression of IQGAP2 in 9 GC cell lines and the human normal gastric mucosal epithelial cell line GES-1 by Western blot and qRT-PCR analyses." (PMID 32183047, 2020). "In contrast, the IQGAP2 transcript levels were reduced across different cancers viz." (PMID 29073199, 2017).